RGPD6 (RANBP2 like and GRIP domain containing 6)
Synonyms: RanBP2L1; RanBP2L2; RGPD7; RGP6
Gene: Protein-coding gene on chromosome 2 (110,513,802 to 110,610,840, reverse strand). Ensembl gene ENSG00000183054.
Subcellular location: Cytoplasm
Subcellular location (Human Protein Atlas): Nuclear membrane; Vesicles
Gene Ontology:
Molecular function: protein binding; SUMO transferase activity
Biological process: NLS-bearing protein import into nucleus; nuclear export
Cellular component: nuclear pore; cytoplasm; Golgi apparatus
Homologues: Orthologues: zebrafish ranbp3a (5% identical), Drosophila melanogaster RanBP3 (5% identical). Paralogues in human: RGPD5 (100% identical), RGPD8 (99% identical), RGPD3 (95% identical), RGPD4 (94% identical), RGPD1 (93% identical), RGPD2 (93% identical), RANBP2 (84% identical), RANBP3 (7% identical), RANBP3L (4% identical), RANBP1 (4% identical).
Diseases named in the same sentence as RGPD6 in open-access papers:
RGPD6 is named in the same sentence as 8 diseases in open-access papers, as found by Europe PMC text mining. Sharing a sentence is not in itself a finding about the gene and the disease. The quoted sentences say what the papers report.
autism spectrum disorder (1 paper, 2024). A spectrum of developmental disorders that includes autism, and Asperger syndrome. "The RGPD6 gene’s association with autism spectrum disorder and intellectual disability underscores potential common symptomatic manifestations across neurodevelopmental disorders." (PMID 39202552, 2024).
developmental delay (1 paper, 2021). "A copy number loss encompassing a similar interval (including MALL, NPHP1, LIMS3, RGPD6, and BUB1) has been reported in ClinVar as a variant of uncertain significance with the phenotype of developmental delay and facial dysmorphisms (SCV000709783.2)." (PMID 33597717, 2021).
liver cirrhosis (1 paper, 2022). "Microduplication of RGPD6 was earlier reported in a family with liver cirrhosis and other diseases." (PMID 35573701, 2022).
cancer (1 paper, 2025). A tumor composed of atypical neoplastic, often pleomorphic cells that invade other tissues. "Upregulation of RGPD6, RGPD5, RGPD8, RGPD2, NUP210L, and PLCL1 has been observed in invasive tumors, implicating this functional network in the remodeling of ECM stiffness and integrin signaling, both of which enhance cancer cell migration." (PMID 40370715, 2025).
RGPD6 also shares sentences with these, for which no sentence is quoted: Intellectual disability (1 paper); neurodevelopmental disorder (1); schizophrenia (1); tumor (1).